MAX (MYC associated transcriptional regulator X)
Diseases named in the same sentence as MAX in open-access papers (continued):
Sharing a sentence is not in itself a finding about the gene and the disease.
neuroblastoma (continued). "Reduction of MAX was observed in some additional neuroblastoma cell lines, apparently irrespective of MYCN amplification status." (PMID 36874405, 2022). "Literature has suggested that some compounds (e.g., 10058-F4 and 10074-G5) can inhibit MAX-MYC heterodimerization and induce growth inhibition, apoptosis, and differentiation in MYCN-amplified neuroblastoma cells, and some compounds can prolong survival of MYCN transgenic mice." (PMID 35056094, 2021). "Utilizing a MYCN-amplified neuroblastoma xenograft tumor model, we could show that MYCMI-6 treatment significantly reduced MYCN:MAX interaction in tumor tissue, suggesting that MYCMI-6 reached and was active against its target in vivo." (PMID 29968736, 2018). "In the first, we have observed that neuroblastoma patients who did not present disease relapse in five years had significant higher levels of MAX expression than patients who either had or were already at relapse." (PMID 24349289, 2013). "Therefore, the impact of the genotype on ODC1 expression in neuroblastoma may depend on the balance of MYCN levels and MAD1/MXI1 levels, and their binding with MAX." (PMID 33918978, 2021). "In this family, the heritability of PCC is linked to the MAX germline variant and not to the KIF1B germline variant which, however, may have contributed to the occurrence of neuroblastoma (NB) in the proband." (PMID 33112832, 2020). "To address whether MAX expression could affect neuroblastoma by activating a differentiation pathway, we have analyzed a dataset of MYCN non-amplified neuroblastoma cells SH-SY5Y subjected to a differentiation protocol." (PMID 24349289, 2013).
breast carcinoma (15 papers, 2009 to 2025). "MAX is a gene implicated in the expression of glycolytic enzymes, influencing breast cancer cell proliferation and migration, as well as anaplastic large cell lymphoma." (PMID 38302916, 2024). "Elevated MAX expression levels have been observed to correlate with breast cancer cell proliferation, glycolytic activity, and migratory potential." (PMID 38611046, 2024). "To validate the effect of MYCMI-7 on endogenous MYC:MAX interactions, isPLA was used in MCF7, a breast cancer cell line we have used extensively to validate the effect of MYC:MAX inhibitors on endogenous MYC:MAX interactions." (PMID 36874405, 2022). "We tested this on the breast cancer cell line MCF7 for which sequence data from both input material as well as multiple ChIPseq experiments for a number of DNA-associated proteins (ER, EGR1, GATA3, CTCF, MAX, and EP300) are available." (PMID 25887352, 2015). "Using the Kaplan-Meier Plotter web tool, we have found that higher MAX expression was associated with improved prognosis in breast cancer, in lung cancer, and not related to prognosis in ovarian cancer cohorts." (PMID 24349289, 2013). "Treatment of breast cancer cells with the MYCMI-6, MYCMI-11 and MYCMI-14 for 24 hours significantly decreased MYC:MAX isPLA signals to 7%, 23% and 23% of DMSO-treated controls, respectively." (PMID 29968736, 2018). "MYC and MAX RNA were detected in circulating breast cancer monocytes (KRT7+, CD11b+, CSF1R+), whole breast cancer tissue (KRT7+, CD11b+, CSF1R+), and isolated breast cancer tumor infiltrating macrophages (KRT7 negative or low, CD11b+, CSF1R+), supporting a potential role for MYC in human TAMs." (PMID 32685002, 2020).
lung carcinoma (11 papers, 2013 to 2024). "Strong evidence for two deleterious germline mutations (rs587781454 in RAD50 and rs756875895 in MAX) has been shown in lung cancer patients." (PMID 34540367, 2021). "Nevertheless, we have also found positive association of MAX expression and improved prognosis in two independent cohorts of breast and lung cancer patients, corroborating its role in disease progression." (PMID 24349289, 2013). "We have detected significant associations between higher MAX expression and improved survival rates for breast and lung cancer patients, suggesting that the clinical predictor potential can also be extended to other types of tumors." (PMID 24349289, 2013). "TLX1::NFIC, MAX and Myc are predicted to have stronger binding affinity in those individuals with the risk allele, highlighting the potential functional role of this SNP in lung cancer." (PMID 24920305, 2014). "The ChIP-Seq data of MYC and MAX at the regulatory regions of LINC00958 in lung cancer cells, including H2171 and SW1271 cells, were retrieved from the GEO database (GSM894103, GSM3073948, and GSM3073949) and plotted." (PMID 35223488, 2022). "As an example of transactivation ability, a SWI/SNF subunit, BRG1, is necessary for MAX gene transcription, MAX-dependent prodifferentiation gene expression, and the subsequent suppression of lung cancer development." (PMID 28101510, 2016).
pituitary adenoma (10 papers, 2015 to 2026). "Out of the patients who had been reported to have PitNETs carrying SDHx/MAX (MYC-associated factor X) mutations, 26% had isolated pituitary adenomas and 19% had a pituitary adenoma first, developing a PPGL after." (PMID 39194755, 2024). "Multiple endocrine tumors have been associated with germline LOF MAX mutations, and these including pituitary adenomas and PNETs; therefore, it has been suggested that germline LOF MAX mutations have been suggested may cause multiple endocrine neoplasia type 5 (MEN5)." (PMID 38038882, 2024). "Additionally, evidence suggests that germinative and somatic inactivating MAX abnormalities lead to tumour risk, namely renal oncocytoma, pituitary adenomas, pancreatic neuroendocrine tumours, small cell lung cancers and Gastrointestinal Stromal Tumours (GIST)." (PMID 33815275, 2021). "Known pheo/PGL genes (SDHA-D, SDHAF2, RET, VHL, TMEM127, MAX, FH) and pituitary adenoma genes (MEN1, AIP, CDKN1B) were sequenced using next generation or Sanger sequencing." (PMID 25494863, 2015). "A host of mutated genes have also been implicated as the cause of acromegaly, AIP in familial isolated pituitary adenoma, SDH subunits in pituitary adenomas in association with pheochromocytomas/paragangliomas (3Pa), mutated MAX gene, and overexpression of GPR101." (PMID 36105896, 2022). "Prior work exploring the DNA methylome showed Myc-Associated Protein X (MAX), a transcription factor involved in cell cycle regulation, was differentially methylated between GHPA and nonfunctional pituitary adenoma (NFPA)." (PMID 37104368, 2023).
small cell lung carcinoma (8 papers, 2017 to 2024). Small cell lung cancer (SCLC) is a highly aggressive malignant neoplasm, accounting for 10-15% of lung cancer cases, characterized byrapid growth, and early metastasis. "MAX is known as a tumor suppressor in small-cell lung cancer." (PMID 38513890, 2024). "Similarly in BRG1-deficient small cell lung cancer, MYC-associated factor X (MAX) was identified as a synthetic lethal target." (PMID 32649682, 2020). "Many reports also showed that MAX is related to the small cell lung cancer (SCLC)." (PMID 29363433, 2018). "MAX is known as a tumor suppressor in renal oncocytomas and small cell lung cancer." (PMID 28651018, 2017).
colorectal cancer (7 papers, 2016 to 2026). A primary or metastatic malignant neoplasm that affects the colon or rectum. "In this study, we identified a novel protein, ANKRD22, which was induced by the TME through activation of p38/MAX pathway and associated with the reprogramming of colorectal cancer cells." (PMID 31903135, 2020). "The SNP rs2238126 G allele may attenuate the regulation of ETV6, which in turn is associated with increased risk of colorectal cancer, most likely by altering the binding affinity of transcriptional enhancer MAX." (PMID 27145994, 2016). "Therefore, the contribution of rs2238126 to the development of colorectal cancer may result from the rs2238126 A allele preferentially binding MAX over the G allele." (PMID 27145994, 2016). "Consequently, the usage of inhibitors of the protein–protein interaction of MYC and NMYC with MAX is a possible treatment strategy for both neuroendocrine- and AC-derived colorectal cancer cell lines that harbor a subpopulation with potential stem-like properties." (PMID 32927768, 2020). "Results obtained with a preclinical TNIK inhibitor in human colorectal cancer cells show efficient abrogation of MYC expression and consequently impaired dimerization with its interaction partner MAX." (PMID 41785318, 2026).
lymphoma (7 papers, 2013 to 2024). A malignant (clonal) proliferation of B- lymphocytes or T- lymphocytes which involves the lymph nodes, bone marrow and/or extranodal sites. "By examining the endogenous interactions with Co-IP, we found that MYC, UBE3B, and MAX (also known as MYC-associated factor X) formed the heterotrimer in lymphoma cells." (PMID 33298911, 2020). "Lindeman and colleagues, however, have elegantly demonstrated that MAX has a more active role decreasing the size and frequency of tumors when overexpressed in lymphoma susceptible mice." (PMID 24349289, 2013). "In MAX knockout Eμ-Myc mice, the levels of MYC protein and its direct target genes were significantly downregulated, and Eμ-Myc-induced lymphomas were almost completely inhibited, implying that MAX-MYC interactions are cell-background specific." (PMID 36352191, 2023). "MYC and MAX expression in lymphoma-derived cell lines was assessed by western blotting." (PMID 32587329, 2020). "Further, MYC, TRIB3, and MAX formed the heterotrimer in lymphoma cells." (PMID 33298911, 2020). "MAX mRNA expression in ALCL cases was significantly lower than that in other T-cell lymphomas (angioimmunoblastic T-cell lymphoma, adult T-cell leukemia/lymphoma, and extranodal natural killer/T-cell lymphoma, nasal type), regardless of MYC mRNA expression." (PMID 32587329, 2020). "The first one to show effect in lymphoma was 10058-F4, which was employed in vitro in different BL cell lines and demonstrated that targeting of MYC/MAX interaction could impair lymphoma growth in a time- and dose-dependent manner." (PMID 37457123, 2023). "MAX expression in ALK-positive ALCL patients was significantly lower than in PTCL-NOS in the GSE65823 dataset, whereas MYC mRNA levels were comparable among these lymphomas." (PMID 32587329, 2020). "Since MYCT1 and MAX are widely expressed in a variety of normal tissues, we speculate that MYCT1 may regulate the expression of RUNX1 at the transcriptional level through interaction with MAX, participating in the occurrence and development of lymphoma." (PMID 38172714, 2024).
metastatic disease (7 papers, 2014 to 2026). "However, in a study of patients with PHEO-associated MAX mutations, five patients were ≤18 yo, of which one had a metastatic tumor." (PMID 29755524, 2018). "Furthermore, our analysis showed that females with PPGL due to MAX PV were diagnosed later than males and presented more often with metastatic disease." (PMID 38481600, 2024). "Metastatic disease is one of the features that indicates likelihood of a hereditary cause, and it is recommended that patients with malignant PCC should undergo genetic testing for SDHB, SDHC, SDHD, VHL and MAX." (PMID 29768630, 2018). "In our analyses of risk rate not adjusted for time, we found a significantly increased risk of metastatic disease in patients with pathogenic germline variants in SDHA, SDHB, SDHC, TMEM127, MAX, and FH compared to those with no identified pathogenic variant." (PMID 41183483, 2026). "No cases of MAX-related metastatic tumors have been reported so far in cohorts of pediatric PHEO." (PMID 29755524, 2018).
acromegaly (5 papers, 2021 to 2026). Acromegaly is an acquired disorder related to excessive production of growth hormone (GH) and characterized by progressive somatic disfigurement (mainly involving the face and extremities) and systemic manifestations. "Acromegaly with MAX mutation: The association of PPGL and PA has been described in a few cases due to MYC-associated factor X mutations (MAX)." (PMID 33805450, 2021). "Another nonsense mutation in the MAX gene (NM_002382) [c.223C>T (p.R75X)] was found in a 38-year-old female associated with pheocromocytoma, prolactinoma, and clinical and biochemical characteristics of acromegaly." (PMID 39194755, 2024). "As for MAX mutations, there are two families known, one with a truncating germline MAX variant (c.22G>T, p.Glu8*) and another with a loss-of-function germline variant (c.200C>A, p.Ala67Asp), with only the last one being associated with acromegaly." (PMID 39194755, 2024). "However, without genetic studies on gene mutations (e.g., AIP, PRKAR1A, GPR101, GNAS, MEN1, CDKN1B, SDHx, MAX, it is difficult to assess whether OL-23/77 was affected by gigantism and acromegaly or just one of these diseases." (PMID 35498425, 2022).
COVID-19 (5 papers, 2022 to 2024). A disease caused by infection with severe acute respiratory syndrome coronavirus 2. "Our analysis demonstrates decreased expression of several MYC and MAX targets in patients with severe COVID-19." (PMID 38262689, 2024). "For example, individuals with moderate COVID-19 demonstrated lower levels of FOSL2, MAX, MAFB, IRF1, RUNX3, and HIF1A in CD14 and CD16 monocytes from other cohorts." (PMID 39712003, 2024). "In COVID-19 interaction, the TF–miRNA network showed that E2F1, MAX, EGR1, YY1, and SRF were the highly expressed TFs, and hsa-miR-19b, hsa-miR-495, hsa-miR-340, hsa-miR-101, and hsa-miR-19a were among significant miRNAs." (PMID 36059456, 2022). "In COVID-19 patients, the DEG–miRNA, and DEG–transcription factors (TFs) interactions network analysis revealed that E2F1, MAX, EGR1, YY1, and SRF were the highly expressed TFs, whereas hsa-miR-19b, hsa-miR-495, hsa-miR-340, hsa-miR-101, and hsa-miR-19a were the overexpressed miRNAs." (PMID 36059456, 2022).
glioma (5 papers, 2019 to 2025). A benign or malignant brain and spinal cord tumor that arises from glial cells (astrocytes, oligodendrocytes, ependymal cells). "Conversely, the protective associations observed with PTK2, CCND2, RAD51L3-RFFL, and MAX suggest potential compensatory or tumor-suppressive functions in glioma." (PMID 41356219, 2025). "Downregulated genes common to different glioma cell cultures are enriched in transcripts controlled by MYC and MAX." (PMID 36231068, 2022). "Inhibition of MYC/MAX alone significantly reduced cell viability to 12%, which concords with the reported contribution of MYC to glioma stem cell maintenance." (PMID 36361720, 2022).
myeloma (5 papers, 2014 to 2022). "MAX mutations have subsequently been described in tumors as diverse as multiple myeloma, small-cell lung cancer (SCLC), pituitary adenoma and quadruple wild-type gastrointestinal stromal tumor." (PMID 35203395, 2022). "Multiple myeloma, in which the MAX mutation rate is ~3%, was a particularly informative source as the Max mutations provided clues into how they impacted the protein’s binding to various epigenetically-modified E-boxes." (PMID 35203395, 2022). "The one exception is those myelomas with loss-of-function mutations in the MYC binding partner MAX, which express MYC at substantially lower levels." (PMID 31015454, 2019). "Furthermore, treatment of c-Myc-expressing myeloma cells with 10058-F4, a specific inhibitor of c-Myc/MAX heterodimerization, resulted in an increase of cytotoxicity, suggesting that there was an addiction to c-Myc for survival in these cancer cells." (PMID 25344919, 2014). "Interestingly, while chr12q24 gains are not present in myeloma, we identified here a significant enrichment of c-MYC/MAX target genes in MM patients characterized by high SETD8 expression, thereby supporting a potential role of this oncogenic pathway in SETD8 deregulation." (PMID 34530900, 2021).
colon carcinoma (4 papers, 2019 to 2025). "Germline MAX variants have been associated with PCC/PGL and renal oncocytoma, while somatic MAX mutations have been linked to the formation of other tumors such as endometrioid carcinoma and colon cancer." (PMID 32973681, 2020). "As opposed to MYC, MAX levels were not consistently altered in colon cancer patient samples." (PMID 31623618, 2019).
neurofibromatosis type 1 (4 papers, 2014 to 2024). A clinically heterogeneous, neurocutaneous genetic disorder characterized by cafe-au-lait spots, iris Lisch nodules, axillary and inguinal freckling, and multiple neurofibromas. "Genetic information was available in 136 patients of the PHEO group, of whom 31.6% had a predisposing hereditary syndrome (27 MEN2A, 6 neurofibromatosis type 1, 4 SDHB mutations, 3 Von Hippel Lindau syndrome, 2 SDHD mutations and 1 patients MAX mutation)." (PMID 35177692, 2022).
pancreatic cancer (4 papers, 2014 to 2024). "We hypothesise that partial depletion of MAX is neutral in pancreatic tumours, since MAX also forms repressive homodimers and heterodimers that bind to similar DNA motifs and compete with the gene-activating capacity of the MYC/MAX heterodimers." (PMID 38821858, 2024).
renal oncocytoma (4 papers, 2017 to 2021). "Renal oncocytoma was described as part of three cases of RAPTAS (two with an SDHB mutation and one with a MAX mutation)." (PMID 28973655, 2017).
anaplastic large cell lymphoma (3 papers, 2020 to 2024). Anaplastic large cell lymphoma (ALCL) is a rare and aggressive peripheral T-cell non-Hodgkin lymphoma, belonging to the group of CD30-positive lymphoproliferative disorders, which affects lymph nodes and extranodal sites. "Recent research also proved that MAX relates to cancer; for example, a decrease of MAX expression might be a latent marker of poor prognosis in anaplastic large cell lymphoma." (PMID 36061355, 2022). "However, the expression and function of MAX in anaplastic large cell lymphoma remain to be elucidated." (PMID 32587329, 2020). "We herein investigated MAX expression in anaplastic large cell lymphoma (ALCL) and peripheral T-cell lymphoma, not otherwise specified (PTCL-NOS) and found 11 of 37 patients (30%) with ALCL lacked MAX expression, whereas 15 of 15 patients (100%) with PTCL-NOS expressed MAX protein." (PMID 32587329, 2020).
ganglioneuroma (3 papers, 2020 to 2024). A benign neuroblastic tumor of the sympathetic nervous system that occurs in childhood. "To date, there have been no reports of ganglioneuroma (GN) with MAX variants." (PMID 32973681, 2020). "Up to now, there have been no reports of ganglioneuroma (GN) with MAX variants." (PMID 32973681, 2020).
gastrointestinal stromal tumor (3 papers, 2020 to 2024). "MAX inactivation represents an early event in the development of gastrointestinal stromal tumors." (PMID 38302916, 2024). "In addition, genomic inactivation of MAX has been recently associated with an MYC-independent progression to malignancy of gastrointestinal stromal tumors, and future studies might reveal the contribution of the clock function of MAX in its paradoxical tumor suppressor role." (PMID 32225100, 2020).
kidney cancer (3 papers, 2021 to 2024). Primary or metastatic malignant neoplasm involving the kidney. "Specifically, when a MAX mutation is present, comprehensive medical history and physical examination are crucial for all carriers of mutations to screen for additional tumors linked to MAX mutations, including PA and renal cancers." (PMID 39121253, 2024). "For instance, HIF1A binds to MAX and disrupts MYC/MAX complexes, leading to reduced cyclin D2 expression, induction of p21 (CDKN1A), and G1 phase cell cycle arrest in human pVHL-null kidney cancer cell lines." (PMID 37998757, 2023).